KRAS (KRas proto-oncogene, GTPase)
Diseases named in the same sentence as KRAS in open-access papers (continued):
Sharing a sentence is not in itself a finding about the gene and the disease.
tumor (continued). "Forty patients (37.7%) had a detectable KRAS mutation (mutKRAS) in codon G12V, G12D or G13D, and four patients (3.7%) had less common mutKRAS on tumour tissue (i.e., G12A = 2; A146T = 1; G12R = 1)." (PMID 33923563, 2021). "Many studies have reported that ctDNA reflects tumor dynamics in many carcinomas, which is consistent with our previous studies monitoring KRAS-mutated ctDNA in pancreatic and colorectal cancer." (PMID 34675229, 2021). "Ultimately, from the perspective of CTCs primarily shedding from tumour tissue, it is also important to analyse EMT/cancer stem cell markers and KRAS mutation status of CTCs besides considering tumour location." (PMID 33462311, 2021). "Unlike AMG510 and MRTX849, which target the specific KRAS G12C mutation, the anti-tumor effect of RGS existed in CRC harboring multiple types of KRAS mutations." (PMID 34347396, 2021). "V941 induces cytotoxic T lymphocyte (CTL)- and memory T cell-dependent immune responses that specifically target and destroy tumor cells harboring these specific KRAS mutations." (PMID 35083149, 2021). "The KRAS exon 3 mutation rate was higher in female patients and in patients with extranodal tumor deposit." (PMID 34335949, 2021). "Adagrasib (MRTX849) is a potent and selective KRAS G12C inhibitor that demonstrated a significant anti-tumor efficacy in all evaluated KRAS G12C mutated cancer models." (PMID 34064352, 2021). "In one study, tumor-infiltrating lymphocytes (TILs) were collected from metastatic lesions of a patient carrying KRAS-G12D mutation." (PMID 34888246, 2021). "KRAS mutations have been detected in both early- and late-stage CRC patients, which indicates that KRAS mutations likely occur in the early stages of tumor development." (PMID 34440178, 2021). "The overall survival of patients with a KRAS A146–mutated tumor was significantly shorter compared with patients with a KRAS G12–mutated tumor (median 10.7 v 26.4 months)." (PMID 34820593, 2021). "In particular, all the selected patients of this cohort had KRAS variants in cfDNA, and most of them also had KRAS variants in the corresponding paired tumor tissues." (PMID 34640513, 2021). "The tumor 1 (70% tumor content) had following mutations: KRAS p.G13D (allelic fraction (AF) = 35.27%), APC p.R283*(AF = 32.94%) and PIK3CA p.E545K(AF = 4.34%)." (PMID 34600484, 2021). "KRAS-mutated tumors presented an increased value at the 25th percentile of maximal SUV (SUVmax) of the metabolic tumor volume (MTV) as well as for the GLCM-derived contrast (AUC = 0.73–0.79, training)." (PMID 34208595, 2021). "Previous studies have established that KRAS G12D mutation rewired the anabolic glucose metabolic network in multiple cancers that is important for tumor growth." (PMID 32703218, 2020). "Τhe impact of variations of KRAS G12/G13 mutation load in cfDNA in the monitoring of tumor burden was investigated in a subset of 14 NSCLC patients with detectable plasma KRAS G12/G13 mutations at baseline (T0)." (PMID 33233668, 2020). "On the other hand, VMP1 expression is activated in PANC-1 human tumor cells carrying mutated (G12D) KRAS." (PMID 32655498, 2020). "Among the 24 PDAC tumours, 8 (33%) found to harbour this KRAS 12th codon mutation, suggesting a congruence with the validation cohort results." (PMID 32552660, 2020). "The first discordant patient (Patient 17), a 79-year-old male patient, harboring a KRAS G12C mutation in the primary tumor showed a G12V KRAS mutation in the corresponding lung lesion." (PMID 33002027, 2020).
tumor (continued). "After a period of time, tumor cells were able to restore drug sensitivity again, suggesting that clonal evolution persisted, and ctDNA can be used to dynamically monitor KRAS mutation levels, providing a basis for reapplication of anti-EGFR drugs." (PMID 32258135, 2020). "Here, we discuss recent reports connecting KRAS mutations with tumour-promoting inflammation and immune modulation caused by KRAS that leads to immune escape in the TME." (PMID 33116132, 2020). "The cabozantinib group had an overall DCR of 38%, ORR at week 12 was 10% (six patients confirmed partial response), and 64% of these patients showed tumor regression, including those with KRAS and EGFR mutations." (PMID 32575417, 2020). "More tumor heterogeneity was found in KRAS mutated patients compared to KRAS wild-type (KRASwt) patients and when using sum of longest diameters versus sum of products of diameters." (PMID 32185612, 2020). "Recently, it has been shown that mutations of KRAS are able to influence cancer metabolism; these mKRAS-induced modifications depend predominantly on tumor type." (PMID 32708575, 2020). "Co-existing genetic events and mutant KRAS allele copy number gains define distinct metabolic profiles and tumor microenvironment, both contributing to differential drug sensitivities in seemingly comparable tumors." (PMID 32560574, 2020). "We established a xenograft tumor model with nude mouse using DLD1 cells with WT or mutated KRAS to examine the effects of AMPK activation on KRAS mutation-mediated anti-EGFR antibody resistance." (PMID 32703218, 2020). "KRAS mutations tended to arise in men (P < 0.001), smokers (P < 0.001) and patients with higher levels of serum tumor markers (P = 0.048)." (PMID 32729257, 2020). "Analysis of a larger patient cohort using the multiplex ddPCR-based assay is required to delineate the prognostic effect of different KRAS mutations in NSCLC tumor tissues." (PMID 33233668, 2020). "In particular, weekly cycles of a three days FMD were sufficient to reduce KRAS mutated tumor growth to the same extent as high-dose vitamin C." (PMID 32393788, 2020). "Mean tumor SUVmax of patients with KRAS mutation was 24.0±9.0 while this value was calculated as 17.7±8.2 in patients without mutation (wild type)." (PMID 32079384, 2020). "The gene mutation rates of tumor tissue in our cohort were generally higher than those in public datasets except KRAS, possibly due to the low depth of whole exon sequencing and racial difference." (PMID 32850360, 2020). "Univariate Cox regression analysis results showed that age, KRAS mutation, pathologic T, pathologic N, pathologic M, tumor stage, and risk score were notably associated with CRC patients' prognosis." (PMID 32908876, 2020). "By comparing the matching tumor derived organoids and primary tumors, we found that the organoids well represented the morphologies and genetic landscape (KRAS, BRAF, mutation and MSI) of the corresponding primary tumor specimens." (PMID 32290033, 2020). "Homozygous mutation of KRAS can lead to senescence, suggesting that physiologically this “onco”-gene can be considered as a tumor suppressor." (PMID 32725342, 2020). "This strategy therefore has the potential to exploit EGFR overexpression in tumours that are otherwise protected from anti-EGFR treatment strategies by reason of their KRAS mutations." (PMID 32913288, 2020). "Anti-tumor activity was confirmed in mice harboring KRAS-mutated NSCLC xenografts and patient-derived xenografts." (PMID 32560574, 2020).
tumor (continued). "KRAS status of the primary tumour shows high concordance with mutation status in tissue sampled from metastases however." (PMID 32866563, 2020). "In the same line, we found that patients harboring the KRAS G12C mutation in tumor tissue had a trend for longer OS, compared to those with KRAS non-G12C mutation subtypes (p = 0.049)." (PMID 33233668, 2020). "Subsequently, we tested Anti-Tumor effects of the two vaccines in vivo both therapeutically and prophylactically in a mouse CT26 tumor model, wherein the mice contained a KRAS G12D mutation." (PMID 32903495, 2020). "Since the most frequently observed KRAS mutation was G12C, we evaluated patient outcomes according to the detection of this mutation in tumor tissue." (PMID 33233668, 2020). "Somatic mutations of EGFR and KRAS are characteristic mutations in lung AC-s that promote accelerated tumor growth and also affect drug response." (PMID 32434541, 2020). "Patients with a KRAS mutation tended to be female, had mucinous, perineural invasive, and polypoid tumor." (PMID 32161617, 2020). "Using human-specific antibodies, KRAS mutation and PD-L1 expression were detected in the patient tumor tissue, corresponding patient-derived organoids." (PMID 33348809, 2020). "Only moderate concordance (72–87% accuracy) between plasma samples and tumor tissue was observed, potentially due to the higher frequency of the KRAS mutation in the plasma samples." (PMID 32471160, 2020). "Given the important role of mutated KRAS for the development and progression of many tumor entities, targeting this oncogenic driver addresses an urgent clinical need." (PMID 32079091, 2020). "The antitumor efficacy of oncogenic mutant-specific gene editing and mRNA-regulating systems were further investigated by western blot and immunohistochemical (IHC) staining in the xenograft tumor tissues that had disrupted KRAS-G12S mutant alleles." (PMID 32308773, 2020). "Most studies suggest that KRAS mutations can enhance PD‐L1 expression, promote T cell infiltration, and enhance tumor immunogenicity." (PMID 32342665, 2020). "The KRAS mutated tumor was reported to be more frequent in female patients with mucinous differentiation and polypoid growth." (PMID 32161617, 2020). "sgRNA library targeting protein-coding genes in KRAS-mutant CRC cell lines used to identify genes associated with reduced tumor growth." (PMID 32765953, 2020). "Establishing the KRAS mutational status of tumor samples is essential in terms of managing patients with various types of cancer." (PMID 33114622, 2020). "Increasing evidence has indicated that KRAS mutations alter miRNA expression and contribute to tumor development and progression." (PMID 32641995, 2020). "The authors suggested that tissue from the primary tumor or from the liver metastasis can be applied for KRAS mutation testing." (PMID 33002027, 2020). "Different KRAS mutation subtypes in tumor tissue have been shown to exhibit distinct associations with patient prognosis and/or therapeutic outcomes." (PMID 33233668, 2020). "Several studies showed that EV-delivered mutated KRAS silencing efficiently reduces tumor proliferation and growth in lung and pancreatic cancer cells and in mouse tumor xenografts." (PMID 33081417, 2020). "KRAS mutations were detected with the help of real-time Polymerase Chain Reaction technique through genomic DNA extracted from paraffin-embedded tumor tissue blocks." (PMID 32079384, 2020).
tumor (continued). "But, in this study, we found relatively lower frequency (i.e. 33%) of KRAS mutation in PDAC tumours." (PMID 32552660, 2020). "Results of this exploratory study revealed association between lipid profile and KRAS status according to primary tumour location." (PMID 32594310, 2020). "The table contains information about patient sex and year of birth, additional to clinical information about the tumor grading, the KRAS mutation, and the recurrence state of the tumor." (PMID 32492856, 2020). "The combination of mutations in the WNT pathway and in the signaling pathway associated with KRAS mutation are crucial for tumor progression in CRC." (PMID 32471160, 2020). "Tumour-associated KRAS mutations are the most prevalent in the three RAS-family isoforms and involve many different amino-acids." (PMID 32591521, 2020). "NGS analysis of this fragmented biopsy specimen containing approximately 41%‐60% estimated tumor cellularity revealed a KRAS mutation (VAF: 53%) and two IDH2 mutations (VAFs: 13% for p.R140Q and 17% for p.R172M) within different alleles." (PMID 32333643, 2020). "Mice administered with DTT-FDmut showed better Anti-Tumor efficacy than those administered with DTT-FDwt in the KRAS G12D mutation containing CT26 tumor model." (PMID 32903495, 2020). "Large numbers of patients were enrolled, and KRAS mutation status and tumor sidedness were analyzed to identify their roles in bone metastasis of CRC." (PMID 33273596, 2020). "Especially in these patients, CEA seems to be a better measure of tumor load when compared to detection of KRAS mutations in ctDNA." (PMID 33237900, 2020). "Several preclinical reports have shown evidence linking oncogenic KRAS mutations and PD-L1 expression in cancers, which reduces the tumour-specific T cells function in the TME." (PMID 33116132, 2020). "The KRAS-mutated group had lower immune and stromal scores while its tumor purity was higher than that in the wild-type group." (PMID 33254149, 2020). "Cox proportional hazards analysis showed positive entotic-CICs, gender, tumor location, and KRAS amplification were all associated with a poor prognosis by both univariate and multivariate analyses." (PMID 32350415, 2020). "With a cross-sectional design involving an observational analytical approach, we determined the relationship of BRAF V600E and KRAS mutations to the location, histopathology, and degree of tumor differentiation in CRC." (PMID 33145020, 2020). "Because of the very low affinity of the drug for KRAS mutations, it was difficult to target these tumor genes directly." (PMID 32486141, 2020). "Approximately 90% of KRAS missense mutations occur in codons 12 or 135, and these mutations are associated with tumor formation." (PMID 33060649, 2020). "Some alterations induced by oncogenic KRAS mutations in cancer promote tumour cell proliferation (mitogenic effects), whereas other immune-modulatory effects allow the tumours to evade immune-mediated attack by creating an immunosuppressive microenvironment." (PMID 33116132, 2020). "Mean tumor SUVmax of patients with a KRAS mutation (24.0±9.0) was found to be significantly higher than those without KRAS mutation (17.7±8.2) (p=0.001)." (PMID 32079384, 2020). "The CIMP pathway, reported in the 20-30% of sporadic CRC, involves the serrated neoplasia pathway and mutations in KRAS 10% (usually B-Raf proto-oncogene serine/threonine kinase—BRAF—wild type) and BRAF~70%." (PMID 32676506, 2020). "As an epigenetic regulator and transcription factor, BRD4, along with its chemical inhibitor JQ1, is strongly implicated in regulation of cell proliferation, survival and tumor growth in KRAS mutated NSCLC in a c-Myc-dependent manner." (PMID 32793596, 2020). "The MAF of serum KRAS exhibited a recurrent tumor tissue KRASG12/13 mutation (B1, B3) showed 3.12 and 2.06% MAF." (PMID 33585224, 2020).
tumor (continued). "The results suggested that tumor tissue and CTCs had 70% identity in the KRAS mutation state, while the BRAF mutation was less consistent." (PMID 32258135, 2020). "Rectal cancers with KRAS mutations have a higher axial tumor length and a larger ratio of axial to longitudinal tumor dimensions on rectal MRI." (PMID 33575207, 2020). "In our opinion based on these results, it can be stated that the plasma level of the KRAS mutation does not reflect the same biological properties of oncological disease as the level of the mutated KRAS oncogene DNA determined in the tumor tissue." (PMID 32867151, 2020). "This analysis revealed that in 2 out of the 3 PDX models, KRAS signalling was significantly elevated in metastatic PDX tissue relative to primary tumor, consistent with the mutational activation observed in the exome-sequence analysis described here." (PMID 32463822, 2020). "This has been extensively studied and observed in the most common KRAS-mutated tumours arising from the epithelial linings of organs, particularly pancreas, colon and lungs." (PMID 33116132, 2020). "These mutations disable GTPase activity, causing tumour-associated KRAS to accumulate in the active GTP-bound conformation." (PMID 33183271, 2020). "Mutant KRAS driven cancers have been implicated in cell signaling and tumour metabolic remodelling in an environment dependent manner, mediated through cross-talk with surrounding stromal compartment and differing according to tissue of origin." (PMID 32594310, 2020). "A recent study of AMG-510, a small molecule that specifically and irreversibly inhibits KRAS G12C, demonstrated anti-tumor activity when administered as monotherapy to patients with KRAS G12C mutated advanced solid tumors." (PMID 32087721, 2020). "This has been highlighted by the findings that KRAS mutant tumours with co-occurring KEAP1 mutations are associated with later stage lung cancer." (PMID 33276631, 2020). "Another recent pooled analysis of studies assessing the role of KRAS mutation in circulating tumor DNA also indicated poorer PFS and OS in KRAS-mutated genotypes." (PMID 32548736, 2020). "Among 35 patients with KRAS G12/G13 mutant tumor samples, 18 patients (51.43%) carried KRAS mutations in plasma and 17 (48.57%) were cfDNA KRAS wild-type." (PMID 33233668, 2020). "In the validation setting, the radiomic signature predicted survival better than KRAS-mutational status and 8-week tumor shrinkage evaluated according to RECIST criteria (AUC = 0.80 vs. AUC = 0.67 for KRAS and AUC = 0.75 for RECIST, p < 0.001)." (PMID 33036490, 2020). "Oncogenic KRAS signaling modulates the tumor environment profoundly, including responses of the immune system towards the tumor, cancer-associated fibroblasts, and angiogenetic responses." (PMID 32244839, 2020). "An acceleration in tumor growth and an earlier appearance of distant metastasis as well as resistance to antiepidermal growth factor receptor are related to KRAS mutations." (PMID 31998419, 2020). "Accordingly, the median OS was 1.64 months (95% CI = 0.46–8.91 months) for pMUT-tWT and 32.45 months (95% CI = 7.66–32.45 months) for patients with KRAS mutations in tumor tissue only." (PMID 33233668, 2020). "Mutations in KRAS leads to constitutively and persistent stimulus-independent activation of downstream pathways affecting tumor growth, proliferation, and survival." (PMID 33324562, 2020). "The collective data suggest that PTEN mutations confer apoptotic resistance, while KRas mutations confer a growth advantage, and the combination yields the capacity for unchecked tumor formation." (PMID 33020304, 2020). "Using ESTIMATE analysis, we observed that the KRAS-mutated group had higher tumor purity, lower immune score, and lower stromal score than the wild-type group." (PMID 33254149, 2020). "Heterogeneity of KRAS mutation in the primary tumor was analyzed in a few studies and found to be 10–20%." (PMID 32725342, 2020).